CFD (complement factor D)
Description:
Serine protease that initiates the alternative pathway of the complement system, a cascade of proteins that leads to phagocytosis and breakdown of pathogens and signaling that strengthens the adaptive immune system. In contrast to other complement pathways (classical, lectin and GZMK) that are directly activated by pathogens or antigen-antibody complexes, the alternative complement pathway is initiated by the spontaneous hydrolysis of complement C3. The alternative complement pathway acts as an amplification loop that enhances complement activation by mediating the formation of C3 and C5 convertases. Activated CFD cleaves factor B (CFB) when the latter is complexed with complement C3b, activating the C3 convertase of the alternative pathway.
Synonyms: DF; PFD; ADN; ADIPSIN
Tractability: Small molecule: a drug acting on it is in phase 2 or 3 trials; a structure with a bound ligand is known; a high-quality ligand is known; it has a high-quality binding pocket. Antibody: a drug acting on it is in phase 2 or 3 trials; UniProt places it where antibodies can reach, with high confidence; its Gene Ontology location is reachable by antibodies, with high confidence; UniProt predicts a signal peptide or a membrane-spanning region. PROTAC: ubiquitination databases record sites on it; a small molecule that binds it is known.
Target class: Enzyme; Protease; Serine protease
Gene: Protein-coding gene on chromosome 19 (859,453 to 869,490, forward strand). Ensembl gene ENSG00000197766.
Subcellular location: Secreted
Pathways (Reactome):
Immune System: Alternative complement activation; Neutrophil degranulation
Hemostasis: Platelet degranulation
Gene Ontology:
Molecular function: serine-type endopeptidase activity; serine-type peptidase activity
Biological process: complement activation, alternative pathway; zymogen activation; complement activation; protein maturation; proteolysis
Cellular component: extracellular exosome; extracellular region; ficolin-1-rich granule lumen; platelet alpha granule lumen; secretory granule lumen
Genetic constraint (gnomAD): Loss-of-function variants: 25 observed, 15.19 expected, observed/expected ratio (o/e) 1.65, 90% interval 1.17 to 1.95. The synonymous counts are far from expectation, so gnomAD's model fits this gene poorly and the ratio says little. Missense variants: 535 observed, 299.98 expected, observed/expected ratio (o/e) 1.78, 90% interval 1.66 to 1.91. Synonymous variants: 242 observed, 137.9 expected, observed/expected ratio (o/e) 1.75, 90% interval 1.58 to 1.93.
Homologues: Orthologues: chimpanzee CFD (98% identical), macaque CFD (96% identical), dog CFD (82% identical), pig CFD (81% identical), guinea pig CFD (74% identical), rat Cfd (68% identical), mouse Cfd (66% identical), tropical clawed frog cfd (45% identical), zebrafish cfd (41% identical). Paralogues in human: F12 (35% identical), KLK10 (33% identical), F9 (32% identical), HGFAC (32% identical), KLKB1 (30% identical), PRSS55 (30% identical), C1S (28% identical), F7 (28% identical), F11 (28% identical), F10 (27% identical), C1R (26% identical), C1RL (25% identical), and 4 more.
Diseases named in the same sentence as CFD in open-access papers:
CFD is named in the same sentence as 91 diseases in open-access papers, as found by Europe PMC text mining. Sharing a sentence is not in itself a finding about the gene and the disease. The quoted sentences say what the papers report.
Obesity (13 papers, 2017 to 2025). Accumulation of substantial excess body fat. "In majority of studies, increased levels of CFD and LEP have been linked to obesity associated BC progression via enhanced TGFβ signalling and MMP modulation." (PMID 34997107, 2022). "This suggests that KSR2 exerts opposite effects on leptin and complement factor D/adipsin expression in fat tissues, which is consistent with changes observed in other models of obesity in mice." (PMID 36342465, 2022). "Factor D (CFD, adipsin) is synthesized solely by adipocytes and its plasma levels are decreased in obesity." (PMID 28559893, 2017). "Herein, we will review the current studies on the function and mechanism of CFD in CVMDs such as hypertension, coronary heart disease, ischemia/reperfusion injury, heart failure, arrhythmia, aortic aneurysm, obesity, insulin resistance, and diabetic cardiomyopathy." (PMID 39416783, 2024). "Five out of the 358 obesity-specific genes, FABP4, CFD, GHR, TNFRSF11B, and LTF, presented significantly decreased expression in TC patients (LFC<−1.44; and p-value < 1e−7)." (PMID 33240576, 2020). "Using the system biology approach, we mined a set of genes influenced by obesity to uncover five genes (FABP4, CFD, GHR, TNFRSF11B, and LTF) as previously unrecognized contributors to the development of TC." (PMID 33240576, 2020). "Further investigation by single cell RNAseq identified four functional molecular endotypes including obesity specific subsets defined by an inflammatory endotype related to immune cell regulation, fibroblast activation and inflammatory signaling, with up‐regulated CXCL12, CFD and CHI3L1 expression." (PMID 37006170, 2023). "(C) Analysis of CFD and C3AR1 expression from liver biopsy samples in patients with MASH, MASLD, obesity without MASLD, and age-matched healthy controls (n=12–16 per group, Welch t test with Holm-Šídák correction for multiple comparisons)." (PMID 39773465, 2025).
COVID-19 (10 papers, 2022 to 2025). A disease caused by infection with severe acute respiratory syndrome coronavirus 2. "In the complement pathway, IVIG treatment decreased levels of C1RL, C8G, and CFD compared to COVID-19 controls." (PMID 40821834, 2025). "Complement factor D antibody reduces endothelial dysfunction, cytokine, and coagulation in the primate COVID-19 model, which highlights the importance of alternative pathway activation in COVID-19." (PMID 38368584, 2024). "Several proteins related to the complement cascade have been shown to be dysregulated in PLWH with COVID-19; for example, complement factor D (CFD), mannan-binding lectin serine protease 2, and VTN levels were significantly elevated compared to those in PLWH and HCs." (PMID 40568587, 2025). "Complement activation was significantly stronger in lung samples from patients with COVID-19 via the lectin and alternative pathway as indicated by deposition of MASP-2, CFD, C3d and C5b9." (PMID 35237273, 2022). "However, radar plots revealed a clear decrease in the average abundance of several complement proteins in IVIG-treated patients compared to both COVID-19 controls and healthy donors, including C1RL, CFD, CD5L, C8G, and CFHR5." (PMID 40821834, 2025). "Of note, we observed a localized downregulation of certain complement factors (C1QB, CFD, and C7) and interferon response genes (IFI6 and ISG15), in contrast to their enrichment in COVID-19 lungs compared to control lungs in our samples and in others analyzed in previous works." (PMID 37858234, 2023). "Additionally, Angpt-2, complement factor D, PAI-1, pentraxtin-3, S100B, tissue factor, TNF-R1, and u-PAR levels were associated with age in patients with severe, but not critical COVID-19." (PMID 39507250, 2024). "Using immunohistochemistry we investigated deposition of complement factors C1q, MASP-2, factor D (CFD), C3c, C3d and C5b-9 as well as myeloperoxidase (MPO) positive neutrophils and SARS-CoV-2 virus particles in lungs and kidneys from 38 patients who died from COVID-19." (PMID 35237273, 2022). "Concentrations of select chemokines (CXCL8, CXCL10, CCL2, CCL3, CCR1) and complement factors (C2, C9, CFD, C4BPA, C5AR1, CR1) were examined at mRNA and protein levels with regard to a COVID-19 course (ICU vs. non-ICU group) and CMV status at different time intervals." (PMID 36232655, 2022).
breast cancer (8 papers, 2021 to 2026). A primary or metastatic malignant neoplasm involving the breast. "Future research should further elucidate the specific mechanisms of ANGPTL4 and CFD in breast cancer and develop clinical detection methods and treatment strategies based on these biomarkers, thereby advancing precision medicine in breast cancer." (PMID 40340806, 2025). "We have reported that adipokine adipsin (CFD) is a mediator of adipocyte-cancer cell interaction in human breast cancers." (PMID 34439392, 2021). "Only KTR14, KRT16, CXCL9, and CFD in BRCA1 Ovarian Cancer and TSPAN7 and CDKN2C in BRCA2 ovarian cancers were highly upregulated, and KANK4, MFGE8, LINC00346, and SA100A1 in BRCA1 mutated breast cancer, and MAGEA4 in BRCA2 breast cancers." (PMID 40647506, 2025). "Increased CFD is associated with worse progression-free survival in colorectal cancer and promotes breast cancer growth and cancer stem cell-like properties, and CFD inhibitor is considered a highly sensitive and specific drug candidate in the therapy of cutaneous squamous cell carcinoma." (PMID 39310420, 2024). "Therefore, targeted intervention strategies against ANGPTL4 and CFD could emerge as novel approaches to improve breast cancer immunotherapy." (PMID 40340806, 2025). "Recent studies have identified iCAF in several tumour types, including pancreatic cancer and breast cancer, using a variety of markers that encompass inflammatory cytokines and other genes (CXCL1, CXCL8, CXCL12, IL6, CFD, DPT)." (PMID 39757146, 2025). "Although the role of CFD in tumors has been demonstrated, such as cutaneous squamous cell carcinoma, colorectal cancer, and breast cancer; the role of CFD in AML has not been widely demonstrated." (PMID 39310420, 2024).
Sepsis (6 papers, 2020 to 2025). Sepsis is defined as life-threatening organ dysfunction caused by a dysregulated host response to infection. "This translational study supports an important role for the serine protease complement factor D (CFD) in sepsis, both in the mouse as well as in humans: in mice, CFD is associated with a significant impact on coagulation by enhanced platelet function in septic wild-type mice." (PMID 34396466, 2021). "The five putative sepsis plasma biomarkers (AT III, CFD, Col1α1, EGFR, Thbs1) revealed certain relationships with clinical laboratory indices related to hematology, biochemistry, blood gas analysis, coagulation function, and immune function." (PMID 40702576, 2025). "Following CLP-induced sepsis, the plasma abundance of AT III, CFD, EGFR, and Thbs1 was significantly reduced at D1, followed by a gradual increase and recovery, whereas Col1α1 did not exhibit this significant trend." (PMID 40702576, 2025). "RT-PCR analysis of PBMCs from 29 sepsis patients and 11 healthy controls revealed significant differential expression of CFD and P2RX1 (p < 0.05), with greater variability observed in the sepsis group." (PMID 41285832, 2025). "ELISA test results indicated that among pediatric patients, the five candidate biomarkers (AT III, CFD, Col1α1, EGFR, Thbs1) all showed varying degrees of decrease in diagnosing sepsis." (PMID 40702576, 2025). "Our single-cell sequencing data demonstrated that sepsis marker genes were highly elevated in CD16+ monocytes, including NAP1L1, CFD, BID, BCL2A1, MALAT1, RNH1, and LILRA5 genes." (PMID 39294473, 2024). "In addition, CD59, SERPINB2, CFD, and P2RX1 can be potential biomarkers for sepsis diagnosis." (PMID 41285832, 2025).
diabetes (5 papers, 2013 to 2025). "Three candidates had potential roles in biochemical and/or immune signaling and hence were pursued in this study: Ras-related associated with diabetes (Rrad), complement factor D (CFD, also known as adipsin) and anaphase promoting complex subunit 7 (AnapC7)." (PMID 23922952, 2013). "In addition, it has been shown that higher levels of circulating CFD are associated with a lower risk of developing diabetes in middle-aged adults 57, and deficiency in complement factor D is closely related to inflammation." (PMID 40027189, 2025). "We identified C4b, CFD, CXCR6, and LIF that were time dependently increased as diabetes progression as non-invasive biomarker candidates for diabetic nephropathy." (PMID 33922243, 2021). "In conclusion, our study provides transcriptomic data of an animal model with progressive diabetes-induced nephrotoxicity, and also demonstrates that C4b, CXCR6, CFD, and LIF are specific and sensitive biomarkers for early detection of diabetic nephropathy." (PMID 33922243, 2021).
heart failure (5 papers, 2020 to 2025). Inability of the heart to pump blood at an adequate rate to meet tissue metabolic requirements. "A different study yielded similar findings, going further to correlate increased serum levels of complement factor D with increased heart failure severity." (PMID 41155225, 2025). "Endogenous production of complement components following myocardial infarction has been shown, and C3 and CFD have been shown to play a role in cardiac remodeling in right heart failure in mice, where C3 and CFD deletion ameliorated heart failure." (PMID 38527066, 2024). "Moreover, patients with heart failure have shown increased levels of alternative pathway activation products like C3bBbP and CFD, correlating with disease severity and worse outcomes." (PMID 41155225, 2025).
endothelial dysfunction (4 papers, 2023 to 2025). In vascular diseases, endothelial dysfunction is a systemic pathological state of the endothelium (the inner lining of blood vessels) and can be broadly defined as an imbalance between vasodilating and vasoconstricting substances produced by (or acting on) the endothelium. "While a deficiency of CFD is rare, studies show that increased circulating levels of CFD lead to cardiovascular issues such as vascular damage, inflammation, and endothelial dysfunction that can contribute to cardiomyopathy." (PMID 41155225, 2025). "Silencing the CFD gene in CiGEnCs attenuated Ang II-induced endothelial cell injury, indicating that CiGEnC-derived CFD may play a role in endothelial dysfunction." (PMID 37188751, 2023). "Moreover, adipsin, a protein of the complement system (complement factor D) secreted by adipocytes at higher rates in obesity, has been shown in epidemiological studies to bear a cross-sectional relationship with inflammation, endothelial dysfunction, and cardiovascular disease." (PMID 41007694, 2025).
geographic atrophy (4 papers, 2018 to 2025). "In the MAHALO phase 2 trial (Genentech) in geographic atrophy, the CFD inhibitor, lampalizumab, slowed disease progression most prominently in individuals with a particular genetic makeup which notably linked to a polymorphism in the CFI gene." (PMID 28986638, 2018). "Complement factor D inhibitors (e.g., lampalizumab and other anti-CFD biologics) have been demonstrated to reduce geographic atrophy progression in AMD, and comparable anti-complement strategies are under investigation in CKD to curb chronic inflammation." (PMID 41393127, 2025). "Alterations to complement factor H (CFH) and complement factor D (CFD) have been related to both conditions, ARMD and geographic atrophy." (PMID 34204630, 2021).
Insulin resistance (4 papers, 2018 to 2024). Increased resistance towards insulin, that is, diminished effectiveness of insulin in reducing blood glucose levels. "Intact C3 and C5 proteins and the cleaved C3a and C5a peptides are reported to act as mediators of inflammation-induced insulin resistance, but a beneficial effect of complement factor D, a protease required for the generation of the C3 convertase, on β-cell function has been demonstrated." (PMID 28921001, 2018). "Six proteins function in regulating glucose homeostasis, insulin resistance, and β-cell function, including SHBG, FETUB, PRG4, GSN, CFD, and TF, among which SHBG and FETUB are markers of insulin sensitivity and the expression of TF in adipose tissue is positively associated with insulin sensitivity." (PMID 38182717, 2024).
colitis (3 papers, 2020 to 2025). Inflammation of the colon. "Thus, CFD deficiency not only changes the composition of the gut microbiota but also promotes the abundance of E. coli in colitis." (PMID 32879431, 2020). "The dominant E. coli were isolated from colitis tissues of mice and found to be sensitive to both CFD- and Reg4-mediated attack complexes." (PMID 32879431, 2020). "Since CFD may be involved in killing gram-negative bacteria such as E. coli, which are related to colitis, CFD expression in gut epithelial cells may play a role in the occurrence and development of colitis." (PMID 32879431, 2020).
gastric cancer (3 papers, 2011 to 2024). A primary or metastatic malignant neoplasm involving the stomach. "In patients with stomach cancers, GPX3, CLEC3B, CFD, GSN, and CCL14 were the leading five genes that were most significantly downregulated." (PMID 33828156, 2021). "Of these 12 genes, 7 genes highly expressed in gastric cancer tissues were down-regulated (ITGB5, TYMS, MYB, APOC1, CBX5, PLA2G2A, KIF20A) and 5 low-expressed genes were up-regulated after vorinostat treatment (SCGB2A1, TCN1, CFD, APLP1, NQO1." (PMID 21931799, 2011).
aortic aneurysm (2 papers, 2024 to 2025). A ruptured aneurysm located in the wall of the proximal portion of the descending aorta proceeding from the arch of the aorta. "In their study, profilin 1 (PFN1) and complement factor D (CFD) were found to be two potential new biomarkers for the diagnosis of aortic aneurysms, and their combination could improve the diagnosis rate of aortic aneurysms." (PMID 40599317, 2025).
chronic kidney disease (2 papers, 2023). Impairment of the renal function secondary to chronic kidney damage persisting for three or more months. "It has been reported that abnormally increased complement factor D (CFD) in the microparticles of endothelial cells in patients with chronic kidney disease (CKD) may play a role in CKD-related vascular disease." (PMID 37188751, 2023).
complement deficiencies (2 papers, 2020 to 2025). "Both rare monogenic traits, such as terminal complement deficiencies of C5-C9, CFD, CFB, CFI, and C3, and common polymorphisms in the CFH/CFHR3 region have been found in association with IMD." (PMID 32067109, 2020). "The lung cross-species signature includes multiple carcinoma-associated genes (TNR, SCD) and, to a lesser extent, genes involved in complement deficiency (CFD, C3) and NAD+ metabolism (NNMT), all of which may be considered aging-associated processes." (PMID 40249926, 2025).
Hepatic steatosis (2 papers, 2009 to 2024). Steatosis is a term used to denote lipid accumulation within hepatocytes. "Deficiency of CD9 in the liver exacerbated diet‐induced hepatic steatosis via complement factor D (CFD) regulated fatty acid metabolism." (PMID 38837628, 2024). "Current study revealed that hepatic deficiency of CD9 exacerbated diet‐induced liver steatosis via complement factor D regulated fatty acid metabolism." (PMID 38837628, 2024). "Liver‐specific CFD deletion abrogated CD9 effects, and overexpressed CFD induced consistent hepatic steatosis observed in CD9 knockdown mice." (PMID 38837628, 2024). "In contrast, network members promoting development of hepatic steatosis, such as PPARγ, SCD, SREBF1, ACOX1, CIDEC and CFD (adipsin) are repressed during early phase and induced during the late phase of hepatic response to HF diets." (PMID 19680557, 2009).
melanoma (2 papers, 2022 to 2023). A malignant, usually aggressive tumor composed of atypical, neoplastic melanocytes. "Similar to the mouse melanoma model data, the S1 population (PDGFRAhi PDPNhi CD34hi) was characterized by the expression of genes involved in the regulation of immune cell recruitment (cytokines: CXCL12; complement factors: CFD, C3, C1S, CFH)." (PMID 36929873, 2023). "A range of other proteases such as Cathepsin S, complement Factor D and members of the Kallikrein protease family were also included in the proteome profiler arrays, however, none of these were detectable in the melanoma conditioned media." (PMID 36005056, 2022).